MET (MET proto-oncogene, receptor tyrosine kinase)
Diseases named in the same sentence as MET in open-access papers (continued):
Sharing a sentence is not in itself a finding about the gene and the disease.
breast tumors (29 papers, 2008 to 2026). "The anti-tumorigenic properties of MET have been reported in several studies associated with indirect action (reduced insulin levels) or direct actions on molecular pathways that regulate breast tumor cell growth and death." (PMID 33108409, 2020). "Furthermore, c-MET overexpression in breast tumors has been found to be associated with disease progression and correlate with poor survival." (PMID 23497677, 2013). "HER2 and MET were found to be co-expressed in HER2-positive breast tumors and further abolishing MET signaling was able to sensitize these cancer cells to Trastuzumab treatment." (PMID 40560045, 2025). "The HGF/c-MET signaling pathway then modulates the breast tumor microenvironment and drives malignant transformation by inducing c-MET dimerization and phosphorylation, which activates downstream pathways such as MAPK and PI3K21." (PMID 40665092, 2025). "In this regard, the clinical usefulness of MET inhibitors in patients harboring breast tumors with high ERβ expression is worth investigating." (PMID 39742369, 2024). "Our analysis of patterns of KPNA2 mutations in cBioPortal and COSMIC revealed that N375S is also present in the MET gene, occurs across a range of cancer types and is detected in 9% of advanced breast tumours." (PMID 35948941, 2022). "As per protein expression associated pathological data in HPA, we found high/medium protein level expression of c-MET in breast tumor tissues." (PMID 36498560, 2022). "On the other hand, silencing matriptase expression in mice delayed breast tumor formation and inhibited tumor growth via down-regulating the c-MET oncogenic pathway." (PMID 28915606, 2017). "Furthermore, a recent study showed that CIN-induced breast tumours which had relapsed and were now KRAS-independent had recurrent novel subclonal copy number amplifications of another oncogene, MET, which encodes the receptor tyrosine kinase cMET." (PMID 37721639, 2023). "In the context of breast tumors, clinical studies have identified a correlation between HGF pathway activation (as determined by c-MET overexpression) and increased tumor size, high tumor grade, and distant metastasis." (PMID 41597220, 2026). "MET is overexpressed in IDC, and regulates breast tumor growth, metastasis and chemoresistance." (PMID 35405500, 2022). "In addition, basal breast tumors are characterized by low ER and PR expression as well as high levels of EGFR, elevated expression of AKT3, CD44 and MET and decreased GATA3 expression; features that are also consistent with each of the HER2 related subgroups investigated in the current study." (PMID 21672245, 2011). "However, CITED4 (as well as CITED2) have been shown to bind and inactivate HIF-1alpha, and in breast tumors, a negative correlation exists between CITED4 and HIF-1alpha protein expression, which would apparently contradict a role for HIF-alpha regulation of c-MET in the current study." (PMID 26243458, 2016).
chordoma (28 papers, 2010 to 2025). Chordomas are rare malignant tumors arising from embryonic remnants of the notochord in axial skeleton. "FISH analysis revealed trisomy of chromosome 7 in 38% of tumor cells, an alteration already reported in chordomas and frequently associated with c-MET overexpression." (PMID 21970335, 2011). "Although chordomas exhibit considerable genetic and phenotypic variability, chromosome 7q31.2, which harbours the cMET receptor, frequently shows gains whereby, MET signalling subsequently controls the survival, migration, and proliferation." (PMID 41442054, 2025). "The ALK/MET inhibitor crizotinib, as a potential therapeutic agent for chordomas, led to a reduction of proliferation markers and the modulation of key DNA repair and cell cycle regulatory genes, with CDC20 and FOXO4 playing a pivotal role." (PMID 41442054, 2025). "For example, ALK/MET inhibitors affected the growth behaviour and cMET phosphorylation state of chordoma cells in different ways and works more efficiently in sacral cells than in clival cells." (PMID 41442054, 2025). "The ALK/MET inhibitor crizotinib, considered a potential treatment for chordomas, reduced proliferation markers and modulated important genes related to DNA repair and cell cycle regulation, with CDC20 and FOXO4 being particularly significant." (PMID 41442054, 2025). "The ALK/MET inhibitor crizotinib affects sacral chordoma cell growth and cMET phosphorylation, making it a potential therapeutic candidate." (PMID 41442054, 2025). "The receptor tyrosine kinase MET and its ligand hepatocyte growth factor are strongly expressed in primary chordoma samples, and chordoma cell lines, particularly of sacral origin, are sensitive to MET inhibition." (PMID 40901948, 2025). "As the majority of chordomas express cMET and its ligand, HGF, and crosstalks between EGFR and MET-signaling exist, we aimed to explore cMET activity in chordoma cell lines and clinical samples." (PMID 34127734, 2021). "It was reported that the expression of PDGFR-α, EGFR and c-MET were increased in spinal chordoma, and tyrosine kinase inhibitor exhibited suppression effects on chordoma cells." (PMID 34868903, 2021). "Two clival and two sacral chordoma cell lines were tested for chromosomal abnormalities of the MET gene locus; we studied the influence of HGF on the autocrine secretion and migration behavior, as well as protein expression and phosphorylation." (PMID 34127734, 2021). "miRNA-1, one of the miRNAs, was observed to significantly under express in chordoma, and re-expression of miRNA-1 in chordoma cell line decreased cell growth and proliferation by targeting on MET." (PMID 29348851, 2017). "In summary, our study shows for the first time that miR-608 and miR-34a are deregulated tumor suppressive miRNAs that act via regulation of EGFR, MET and apoptosis in chordoma." (PMID 24621885, 2014). "EGFR and MET expression and gene amplification in chordoma in published immunohistochemical studies." (PMID 24621885, 2014). "MET is overexpressed in up to 100% of chordoma as determined by a study of 66 tumor samples among which about 50% showed gene amplification." (PMID 24621885, 2014). "To confirm the expression of EGFR and MET in chordoma specimens, we performed immunohistochemistry on chordoma tumor sections." (PMID 24621885, 2014). "We analyzed the correlation of miR-34a and MET expressions in chordoma cells and found that miR-34a level inversely correlated with MET protein levels (R2 = 0.61, P<0.05)." (PMID 24621885, 2014). "Among the very few molecular dysregulations that have been associated with chordoma malignancy are the frequent dysregulations of the receptor tyrosine kinases (RTKs), EGFR, PDGFR and MET." (PMID 24621885, 2014). "We measured miR-34a levels by qRT-PCR and MET protein levels by immunoblotting in chordoma cell lines, primary cells and normal fibroblasts." (PMID 24621885, 2014).
chordoma (continued). "These were miR-608, which has potential binding sites in the 3′UTR of EGFR and Bcl-xL mRNAs (which are overexpressed in almost all chordoma tumors) and miR-34a which is predicted to target MET (expressed in up to 100% of chordomas)." (PMID 24621885, 2014). "We show that EGFR and MET activations promote chordoma cell proliferation and invasion and that pharmacological inhibition of EGFR and MET inhibits chordoma cell proliferation and survival." (PMID 24621885, 2014). "MET is part of a receptor tyrosine kinase family of oncogenes overexpressed in many human cancers, including sarcomas, particularly in chordoma (94.4%), chondrosarcoma (54.2%), and osteosarcoma (23.3%)." (PMID 22550419, 2012). "Furthermore, a screening of 133 approved cancer drugs, which included tyrosine kinase inhibitors, HDAC inhibitors, and proteasome inhibitors, the ALK/MET inhibitor crizotinib demonstrated promising potential for standard chemotherapy regimens for chordomas." (PMID 41442054, 2025). "We then determined the effects of EGFR and MET activations on chordoma malignancy endpoints." (PMID 24621885, 2014). "We found high expressions of EGFR and MET in chordoma specimens." (PMID 24621885, 2014). "Therefore, copy number alterations of miR-34a and miR-608 are likely partly responsible for EGFR, MET and Bcl-xL overexpressions in chordoma as demonstrated by our study." (PMID 24621885, 2014). "EGFR and MET are among very few molecules that have been shown to be deregulated in human chordoma." (PMID 24621885, 2014). "Reintroduction of miR-1 inhibited the growth of chordoma cells, with suppression of MET expression." (PMID 22550419, 2012). "Thus, loss of miR-608 or miR-34a could enhance chordoma malignancy by inducing overexpression of EGFR, MET and inhibiting apoptosis." (PMID 24621885, 2014). "In addition, expression of the MET oncogene has been reported in chordoma." (PMID 22613809, 2011). "Chordomas commonly activate pathways such as EGFR, PDGFβ, IGFR1, IGF1, mTOR, MET, and PI3K and involve chromatin remodeling genes such as ARID1A, PBRM1, and SETD2." (PMID 39193055, 2024). "Immunohistochemical (IHC) studies have shown that RTKs, such as platelet-derived growth factor receptor (PDGFR), epidermal growth factor receptor (EGFR), MET and HER2, are expressed in chordoma." (PMID 32533822, 2020). "A recent study reported that most chordomas express multiple RTKs, including PDGFR isoforms, EGFR, HER2, c-MET, and KIT." (PMID 27200287, 2016). "We find that miR-34a inversely correlates with MET expression and miR-608 inversely correlates with EGFR expression in chordoma cells." (PMID 24621885, 2014). "In fact, studies have found that 27–40% of chordomas have amplified EGFR and 27–50% have amlplified MET genes." (PMID 24621885, 2014). "We activated EGFR with EGF (20 ng/ml) or MET with HGF (20 ng/ml) treatment in UCH1 and C24 chordoma cells." (PMID 24621885, 2014). "The receptor tyrosine kinase MET and its ligand hepatocyte growth factor (HGF) are expressed in a variety of solid tumors, including chordomas and have emerged as key determinants of tumor growth and invasion." (PMID 24621885, 2014). "We therefore identified and characterized miR-608 and miR-34a as novel tumor suppressive miRNAs in chordoma that directly target EGFR, Bcl-xL or MET." (PMID 24621885, 2014). "We chose miR-608 and miR-34a for further study because their chromosomal loci are frequently deleted in chordoma and because they are predicted to target EGFR and MET, which are the most commonly deregulated RTKs in chordoma." (PMID 24621885, 2014). "In the literature, several RTK, specifically PDGFRA, PDGFRB, KIT, EGFR, MET and HER2, were reported to be expressed in chordoma by immunohistochemistry." (PMID 22613809, 2011).
chordoma (continued). "Despite the identification of numerous genes with dysregulated expression in vitro or in vivo in chordoma (e.g. brachyury, EGFR, Ezrin, MMP-9, c-MET, FHIT, etc.) conventional or targeted chemotherapeutic agents showed a partial response at best-case scenarios in clinical case-series." (PMID 36033338, 2022). "Our micro-array data revealed that a large number of genes were differentially expressed in chordoma tissues, including EGFR, PDGFRβ, IGF-1R and MET etc., which have been identified to the potential therapeutic targets in chordoma with both clinical and molecular evidence." (PMID 29348851, 2017). "It was shown that 67–100% of chordomas overexpress EGFR and 70–100% overexpress MET." (PMID 24621885, 2014). "Overexpression of MET and HGF in chordoma enhances cell survival and invasion." (PMID 24621885, 2014). "MET expression was shown previously in chordomas by several other groups, but MSPR expression and activation was only recently reported in all three investigated chordomas by Shalaby and co-workers." (PMID 22613809, 2011). "We observed that EGFR (fold change: 2.652), MET (fold change: 4.676), AKT3 (fold change: 3.703) and EGF (fold change: 11.094) which is a ligand of EGFR, were down regulated in chordomas without dural penetration." (PMID 32533822, 2020).
kidney cancer (28 papers, 2014 to 2025). Primary or metastatic malignant neoplasm involving the kidney. "To search for a molecular therapeutic target for BHD-associated kidney cancer, we compared DEGs identified in BHD-associated kidney cancers with DEGs in other cancers analyzed in this study, and found that MET was highly expressed in BHD-associated kidney cancers." (PMID 35874919, 2022). "Finally, using anti-MET immunohistochemistry, we confirmed that MET protein expression was greater in BHD-associated kidney cancers than in adjacent normal kidney tissue." (PMID 35874919, 2022). "In the present study, we found that MET expression was high in various histological types of BHD-associated kidney cancer, raising the possibility that MET inhibitors, such as cabozantinib and crizotinib, may provide promising therapeutic approaches for treatment of BHD-associated kidney cancer." (PMID 35874919, 2022). "There are many reports on genes associated with kidney cancer pathogenesis, including VHL, FH, MET, FLCN, etc.." (PMID 32850947, 2020). "The C-met oncogene encodes the hepatocyte growth factor receptor, and we observed increased MET levels in the kidney cancer data." (PMID 28178311, 2017). "Bulk RNA-seq datasets from 16 BHD-associated kidney cancers and 5 normal kidneys further showed that the expression levels of MET (p < 0.001) and vascular endothelial growth factor B (VEGFB) (p < 0.001) in BHD-associated kidney cancers were statistically higher than those in normal kidneys." (PMID 35874919, 2022). "The findings suggest that genes associated with kidney cancer, including VHL, MET, FH, FLCN, TSC1, TSC2, and SDH, are involved in metabolic pathways linked to oxygen and iron or nutrient sensing, thus characterizing kidney cancer as a cellular metabolic disease." (PMID 35873461, 2022). "Multiple genes linked with kidney cancer, including the VHL, MET, FLCN, fumarate hydratase, succinate dehydrogenase, TSC1, TSC2, and TFE3, were identified by genomic studies and have significantly altered the ways in which patients with kidney cancer are managed." (PMID 29254180, 2017). "Recently, several characteristic kidney cancer-related genes, including VHL, MET, FLCN, TSC1, TSC2, FH, and SDH, have been reported to affect the metabolic stress response." (PMID 33686951, 2021). "Previous studies have shown that seven known kidney cancer genes, VHL, MET, FLCN, TSC1, TSC2, FH, and SDH, are involved in pathways that respond to metabolic stress or nutrient stimulation, suggesting that kidney cancer is a disease of dysregulated cellular metabolism." (PMID 31649873, 2019). "Interestingly, kidney cancer has been suggested as a metabolic disease, many kidney cancer genes like VHL, MET and TSC1/2 are involved in metabolism-related pathways." (PMID 25408144, 2014).
gastric tumors (27 papers, 2008 to 2024). "In this study, we discovered that AFP enhances the stability of oncoproteins c-MYC and c-MET, thereby facilitating the progression of liver and gastric tumors." (PMID 39135041, 2024). "Catenacci and colleagues reported a case of complete response in a patient with advanced gastric tumor and MET gene polysomy between four and six copies, but it was associated with a high serum HGF level." (PMID 28960893, 2017). "Previously, receptor tyrosine kinase genomic alterations were detected in 20.6% of cases, affecting ERBB2, FGFR2, and MET, suggesting potential benefit from targeted therapy including MET-amplified gastric tumors and ERBB2 base substitutions." (PMID 27384994, 2016). "Specifically, we focused on the miR-1 target gene MET to determine its expression in gastric tumor tissues." (PMID 25874496, 2015). "On the other hand, focal MET gene amplification appears rare in treatment-naïve gastric tumors with reported incidences of between 0 – 5%." (PMID 24930887, 2014). "Recent retrospective IHC studies on gastric tumor tissues obtained following tumor resections have reported MET overexpression in 4% - 63% of cases." (PMID 24930887, 2014). "It remains to be seen if HGF expression with gastric tumors can be reliably measured and if it proves to be a clinically useful biomarker to select patients for anti-MET therapy." (PMID 24930887, 2014). "In preclinical models, MET gene amplification results in constitutive activation of the MET receptor and an oncogenic addiction to the MET signaling pathway thereby rendering gastric tumor cells acutely sensitive to HGF/MET axis inhibition." (PMID 24930887, 2014). "c-MET (pY1003) phosphorylation was detected in only two gastric tumor lysates (G2, G3) and these same tumors were also positive for HGF/c-MET complexes by proximity FFPE assay." (PMID 21283737, 2011). "In one gastric tumor lysate (G6), a slightly higher molecular weight/slower migrating band that also reacted with the c-MET (pY1003), however, at the present time, the identity of this protein is uncertain (Fig. 9Dii)." (PMID 21283737, 2011). "Finally, MET expression was evaluated by immunohistochemistry in a stomach tumor tissue microarray (TMA)." (PMID 25874496, 2015). "In fact, gastric tumors that display MET gene amplification (10% of cases) are potentially addicted to MET expression and can be considered ideal targets for anti-MET therapies; however, aberrant activation of HER family members has also been shown to be concomitant in these tumors." (PMID 20500904, 2010). "Normal gastric mucosa and gastric tumor tissues were compared for ARID1A, CDH1, c-MET and PIK3CA mRNA expression using RT-qPCR." (PMID 26334097, 2015). "We also compared our HGF/c-MET measurements in the proximity FFPE assay with the levels of c-MET (pY1003), c-MET (pY1234/1235), and c-MET (pY1349) phosphorylation detected in NSCLC and gastric tumors." (PMID 21283737, 2011). "The combined overexpression of MET, HER2 and EGFR was observed in 3% of gastric tumors." (PMID 31557260, 2019). "Gastric tumors with neural invasion significantly show high expression of c-MET (83%) compared to those without neural invasion (53%) (P = 0.002)." (PMID 22640970, 2012). "Our attempts to detect c-MET (pY1234/1235) and c-MET (pY1349) phosphorylation in NSCLC and gastric tumors were unsuccessful (data not shown) suggesting that phosphorylation at these sites might be labile than c-MET (pY1003)." (PMID 21283737, 2011).